TSPAN17 (tetraspanin 17)
Description:
Part of TspanC8 subgroup, composed of 6 members that interact with the transmembrane metalloprotease ADAM10. This interaction is required for ADAM10 exit from the endoplasmic reticulum and for enzymatic maturation and trafficking to the cell surface as well as substrate specificity. Different TspanC8/ADAM10 complexes have distinct substrates. Seems to regulate VE-cadherin expression in endothelial cells probably through interaction with ADAM10, promoting leukocyte transmigration.
Synonyms: FBXO23; TM4SF17; FBX23
Tractability: Antibody: UniProt places it where antibodies can reach, with medium confidence; UniProt predicts a signal peptide or a membrane-spanning region; its Gene Ontology location is reachable by antibodies, with medium confidence.
Gene: Protein-coding gene on chromosome 5 (176,647,387 to 176,659,058, forward strand). Ensembl gene ENSG00000048140.
Subcellular location: Cell membrane
Gene Ontology:
Molecular function: enzyme binding
Biological process: establishment of protein localization to organelle; regulation of membrane protein ectodomain proteolysis; SCF-dependent proteasomal ubiquitin-dependent protein catabolic process
Cellular component: plasma membrane; SCF ubiquitin ligase complex; membrane
Genetic constraint (gnomAD): Loss-of-function variants: 35 observed, 42.21 expected, observed/expected ratio (o/e) 0.83, 90% interval 0.63 to 1.1. The upper end of that interval is the gene's LOEUF score, 1.1, which puts it in group 4 of 6, group 1 being the genes least tolerant of losing a copy. Missense variants: 365 observed, 428.97 expected, observed/expected ratio (o/e) 0.85, 90% interval 0.78 to 0.93. Synonymous variants: 166 observed, 175.38 expected, observed/expected ratio (o/e) 0.95, 90% interval 0.83 to 1.08.
Homologues: Orthologues: chimpanzee TSPAN17 (99% identical), macaque TSPAN17 (98% identical), pig TSPAN17 (84% identical), guinea pig TSPAN17 (81% identical), rat Tspan17 (79% identical), mouse Tspan17 (79% identical), dog TSPAN17 (77% identical), tropical clawed frog tspan17 (73% identical), zebrafish tspan17 (71% identical). Paralogues in human: TSPAN5 (64% identical), TSPAN14 (47% identical), TSPAN33 (31% identical), TSPAN15 (23% identical), CD151 (22% identical), TSPAN9 (22% identical), TSPAN11 (22% identical), TSPAN8 (22% identical), TSPAN4 (22% identical), TSPAN10 (21% identical), TSPAN18 (21% identical), CD82 (21% identical), and 20 more.
Diseases named in the same sentence as TSPAN17 in open-access papers:
TSPAN17 is named in the same sentence as 5 diseases in open-access papers, as found by Europe PMC text mining. Sharing a sentence is not in itself a finding about the gene and the disease. The quoted sentences say what the papers report.
glioblastoma (1 paper, 2024). The most malignant astrocytic tumor (WHO grade IV). "On the other hand, in glioblastoma multiforme (GBM), Tspan17 has an anti-apoptotic function, as it is associated with poor prognosis in GBM patients." (PMID 38649381, 2024).
tumor (2 papers, 2009 to 2022). "Splice variants generated with some of those specific intron junctures in CD82 and TSPAN 32 from group CD63L have been reported in normal and tumor tissues and from TSPAN17, TSPAN 31 from groups TSPAN15L and TSPAN13L (mRNA variants hApr07 and jApr07 from NCBI AceView) respectively." (PMID 19262691, 2009).
TSPAN17 also shares sentences with these, for which no sentence is quoted: breast carcinoma (1 paper); hepatocellular carcinoma (1); infection (1).